BRAF (B-Raf proto-oncogene, serine/threonine kinase)
Diseases named in the same sentence as BRAF in open-access papers (continued):
Sharing a sentence is not in itself a finding about the gene and the disease.
tumor (continued). "Thus, the potential roles of BRAF mutation in the regulation of DNA methylation and tumor initiation deserve further investigation." (PMID 35910024, 2022). "The tumor was positive for the V600 mutation-specific BRAF antibody (BRAF1)." (PMID 35120551, 2022). "One patient’s tumor carried the BRAF V600E mutation and was pMMR." (PMID 34991708, 2022). "The application of an ERK1/2 kinase inhibitor could relieve MAPK inhibitor resistance in tumor cells with BRAF mutations." (PMID 36539659, 2022). "Importantly, this information is essential to effectively modulate tumor metabolism and improve therapies for BRAF mutated cancers." (PMID 35565240, 2022). "MUC5AC protein expression correlated with aggressive tumor features (e.g., distant metastases (p = 0.0334), BRAF mutation (p < 0.0001), mismatch repair-deficiency (p < 0.0001), and unfavorable 5-year overall survival (44% versus 65% for positive/negative staining)." (PMID 34475526, 2022). "However, during the conduct of the trial, information on primary tumor location and BRAF V600E mutation will be collected and considered for subgroup analyses to further clarify this issue." (PMID 35897060, 2022). "Therefore, it is assumed that BRAF mutations in the DFG motif cause tumor development through its enhanced interaction with RAS mutant proteins." (PMID 35163468, 2022). "The clinical features of GeneClusters A and B resemble the difference between ERcluster A and B. In addition to a higher proportion of BRAF mutations, and dMMR and proximal tumor ratios in GeneCluster B, GeneCluster B also had a higher percentage of patients with stage III/IV disease." (PMID 35884393, 2022). "One tumour showed a loss of the 5′ signal suggesting a BRAF rearrangement." (PMID 35836307, 2022). "Whether TIM3 blockade alone or in combination with BRAF plus MEK inhibitors (currently FDA-approved for use in BRAF-mutated ATC) will eliminate tumor growth in vivo would be interesting to address in future studies." (PMID 36358310, 2022). "The treatment of mCRC is based on the combination of polychemotherapy schemes based on oxaliplatin and/or irinotecan associated with biological agents, such as anti-EGFR or antiangiogenic agents, depending on parameters such as the mutational status of RAS and BRAF or tumor sidedness." (PMID 35657983, 2022). "Because of the genetic heterogeneity commonly observed in tumor samples, it is unclear if these secondary mutations were already present in some sub-populations of BRAF V600E tumor cells, or if BRAF inhibitor treatment itself drives the accumulation of additional mutations." (PMID 36358868, 2022). "Thus, the results indicated that PTC patients with a higher tumor stage or neoplasm disease stage had a higher BRAF mutation frequency." (PMID 35757399, 2022). "MiR-193a, one of the candidate miRNAs in BRAF-mutated cells, acts as a tumor suppressor by regulating multiple cancer-related genes and affects cellular sensitivity to MAPK-related pathway inhibitors, such as BRAF inhibitors, MEK inhibitors, and, or anti-EGFR antibodies." (PMID 35465317, 2022). "Molecular-targeted therapy with BRAF and MEK inhibitors for PCP with BRAF mutation may achieve the goal of reducing tumor volume, thus becoming a neoteric treatment for PCP." (PMID 35432485, 2022). "No study has yet demonstrated whether specific secondary mutations found in BRAF-inhibitor resistant tumor samples are the direct cause of BRAF inhibitor resistance, or if such genetic variants are only associated with resistance." (PMID 36358868, 2022). "Among the top 20 mutation genes, mutation in BRAF gene accounted for 78% of tumor samples, suggesting that BRAF mutation might be correlated with the development of invasive thyroid carcinoma." (PMID 35692574, 2022).
tumor (continued). "Future studies are required to confirm the validity of looking for BRAF V600E mutation in peripheral blood (liquid biopsy) prior to surgery (which may mobilize tumor cells into the general circulation)." (PMID 35757402, 2022). "In most cases, the baseline RAS/BRAF mutation was also detected at PD, suggesting that these variants might contribute to tumor progression, but also that additional genomic events are required to drive resistance to both anti-EGFR agents and chemotherapy." (PMID 35205799, 2022). "Further characterization of heterogenous tumor development in our current model might be accomplished by adopting BaseScopeTMin situ detection of driver point mutations, like BRAF V600E, as recently developed for human tumor tissues." (PMID 34379110, 2022). "According to previous reports, this may be related to PD-1 inhibitors altering BRAF abundance and increasing BRAF mutation-associated tumor-associated lymphocytes via the mitogen-activated protein kinase (MAPK) pathway." (PMID 36119532, 2022). "The pro-tumor behavior of infiltrating immune cells may be related to a higher BRAF V600E point mutation rate." (PMID 36531470, 2022). "In addition, the concurrence of BRAF mutations with TERT promoter mutations in CM is linked to a higher tumor aggressiveness." (PMID 36143375, 2022). "DNA methylation profiling classified the BRAF‐mutated tumours as “LGG, GG”." (PMID 35836307, 2022). "Moreover, OCs can be divided in type I (low-grade tumor with BRAF and KRAS mutations) or type II (high-grade tumor with a variety of mutations including HOX, PTEN, KRAS, AKT1, BRCA1/2 genes) and various dysregulated mechanisms underlying the pathology." (PMID 36191006, 2022). "Six tumors exhibited a BRAF V600E and one tumor carried a BRAF V600K mutation." (PMID 35361262, 2022). "BRAF mutations are present almost exclusively in serrated pathway neoplasms and exclude LS." (PMID 35993526, 2022). "It is suggested that a different comparator (FOLFOX in this study) or molecular heterogeneity of mutated BRAF tumours could explain these discordant results." (PMID 36819812, 2022). "WES identified a BRAF D594G mutation in six of seven tumor samples." (PMID 35198414, 2022). "Even so, important advances concerning the identification of tumour markers with clinical applications at the diagnosis, prognosis and therapeutic levels have recently been made, for example, the identification of pathological BRAF mutations." (PMID 35324835, 2022). "Several other studies show a link between large tumor size and BRAF mutations." (PMID 35646190, 2022). "Molecular testing of the tumor was positive for BRAF p.V600E (c.1799 T > A) variant." (PMID 35841038, 2022). "The incidence of BRAF gene mutation is specific for each tumor and varies by geographic location." (PMID 36277559, 2022). "A temporal lobe cystic and solid enhancing tumor in a patient younger than 55 years should prompt next-generation sequencing of the tumor for BRAF mutation, in case targeted therapy may be initiated." (PMID 36233828, 2022). "Interestingly, BRAF mutations have also been detected in other tumor types including colorectal and brain cancers." (PMID 35234863, 2022). "Therefore, validation for the impact of number of tumor foci is required in other subtypes of PTC along with BRAF mutation analysis." (PMID 36077678, 2022). "Moreover, the genetic profile revealed mutation concordance between the CTCs and primary tumour with regard to the activating variant c.1799 T > A in the BRAF gene responsible for the pathogenic p.Val600Glu (V600E, rs113488022) missense mutation." (PMID 35820816, 2022).
tumor (continued). "In addition, a higher percentage of mucin correlated with lower tumor budding (p = 0.0241), higher Klintrup–Mäkinen score (p = 0.0577) and BRAF mutation (p = 0.0329)." (PMID 34475526, 2022). "This indicates that cfDNA analysis may be used to confirm BRAF mutations status as an alternative to tumor biopsy." (PMID 36058945, 2022). "However, a relevant result was that PTC with detectable circulating BRAFV600E showed a higher percentage of BRAF-mutated alleles in the primary tumor tissue." (PMID 36358788, 2022). "Whether such differences in the composition of myeloid infiltrates and their relative enrichment by Activin-A depend on BRAF status or other tumor-specific driver mutations is unknown." (PMID 35580932, 2022). "Indeed, when considering the copies/mL of the mutated subgroup, we observed a trend towards lower RAS/BRAF plasma MAFs in patients with lower tumor burden (defined as total tumor volume)." (PMID 34680277, 2021). "Further studies exploring the impact of the primary tumor side on the prognostic outcomes of BRAF-mutated mCRC treated with anti-EGFR agents may be quite valuable." (PMID 34946284, 2021). "However, the most clinically actionable mutations for this tumour type (BRAF and NRAS) were found to be concordant." (PMID 33435284, 2021). "In support of the results obtained from patient 1, among the liquid biopsies obtained from patient 4, only the time point 3 blood sample, collected after confirmation of radiological PD, demonstrated the BRAF V600E mutation that the primary tumor and peritoneal dissemination possessed." (PMID 34840814, 2021). "Activating BRAF mutations were detected in 7/30 (23%) tumours." (PMID 33737597, 2021). "Although the role of tumor location in the prognosis of BRAF-mutated mCRC remains controversial, it may have some impact with the concomitant use of target therapy such as bevacizumab or cetuximab." (PMID 34946284, 2021). "Treatment with MEKi Trametinib augmented oHSV oncolytic activity in BRAF V600E-mutated tumor cells." (PMID 34578339, 2021). "The tumor-plasma concordance of the non-BRAF mutations was 28%." (PMID 34356096, 2021). "Apart from the conventional pathway that is typically initiated by characteristic APC mutation and chromosomal instability, the serrated neoplasia pathway is mainly characterized by mutations of BRAF or KRAS, microsatellite instability (MSI), and CpG island methylator phenotype (CIMP)." (PMID 33382354, 2021). "Indeed, following tumor progression on osimertinib related to the occurrence of a BRAF V600 mutation, osimertinib was first stopped and the dabrafenib plus trametinib combination initiated." (PMID 34575554, 2021). "It is thought that the worst progression of proximal tumours could be attributed in part to the frequency with which genetic alterations, such as BRAF and KRAS mutations, microsatellite instability, and CpG island methylator phenotype, are detected." (PMID 34557315, 2021). "The plasma-tumor concordance of the non-BRAF mutations was 28%." (PMID 34356096, 2021). "Similarly, the PTC rates were highly variable ranging from 1 to 56% as well as the proportions of BRAF mutated PTC tumours from 0 to 24%." (PMID 32638211, 2021). "This pathway is characterized by an epigenetic mechanism that involves abnormal methylation of CpG islands in the promoter regions of tumor suppressor genes and may be associated with mutations of the BRAF oncogene." (PMID 35118001, 2021). "Because TCGA tumors are primary and treatment‐naive, this observation suggests that BRAF amplification and BRAFV600E may be a sufficient combination for tumor formation, and a cause of intrinsic resistance to BRAF inhibition." (PMID 33769711, 2021). "According to National Comprehensive Cancer Network (NCCN) and American Society of Clinical Oncology (ASCO) guidelines, the detection of RAS and BRAF mutations is routinely carried out in tumor tissue from either biopsies or resected specimens of the primary tumor or of a metastatic lesion." (PMID 34680277, 2021).
tumor (continued). "Only a small minority of patients were determined to have a BRAF mutation or MSI-H tumour (<3%)." (PMID 33208919, 2021). "The estimated MSCs of BRAF mutations among tumor types are consistent with these known facts." (PMID 34424899, 2021). "It is noted that the viral yields increased significantly in BRAF V600E-mutated tumor cells, about 8.6-fold for Widr cell and 6.7-fold for HT29 cell, respectively, when combination of oHSV and Trametinib at the concentration of 15 nM compared to oHSV alone at 72 hpi." (PMID 34578339, 2021). "Here, studies in this manuscript tested whether the combination with oHSV and MEKi Trametinib can enhance oncolytic virus replication and oncolytic activity in BRAF-mutated or RAS-mutated tumor in vitro as well as the antitumor efficacy in vivo." (PMID 34578339, 2021). "The high degree of spatial heterogeneity observed for SNVs in druggable target genes is exemplified by the ALK R1275Q mutation only being detected in 2 of 7 locations in the relapse tumour, the BRAF V600E mutation in only 3 of 7 locations and the FGFR1 N557K mutation in only 5 of 7 locations." (PMID 34815394, 2021). "The p.V600E BRAF mutations was observed in 5/7 (71%) tumours." (PMID 33737597, 2021). "Since the early 2000s, BRAF has been identified as a commonly mutated gene in human tumours." (PMID 33801689, 2021). "No impact of WBRT, RIT, chemotherapy, sex, interval years, pathology, thyroid surgery, pathological features(tumor size, lymph nodes metastases, vascular Invasion, BRAF mutation), any other distant transfer lesions, or presence of neurologic symptoms at BM diagnosis was found." (PMID 34603207, 2021). "Then, we sought to determine whether the MEKi treatment can enhance the oHSV replication in the tumor cells with BRAF wt and the upstream KRAS mutations." (PMID 34578339, 2021). "If a BRAF mutation is present in a dMMR/MSI tumor, Lynch syndrome can be mostly excluded." (PMID 34259881, 2021). "For example, tumours with the BRAF V600E mutation tend to be more severe." (PMID 34123356, 2021). "In our comparison of multi-RFA and hepatectomy, the ECOG status (p = 0.014), presence of comorbidities (p = 0.046), high tumor grade (p < 0.001), initial metastasis (p = 0.002), BRAF-mutated tumors (p = 0.015), and a history of RT (p = 0.002) were predictors of poorer OS." (PMID 34442007, 2021). "Therefore, the status of the BRAF V600E mutation with an EZH2 gene copy number variation can be used as a potential tumor therapeutic target." (PMID 34001246, 2021). "BRAF mutations found in tumours are classified into three types." (PMID 33562094, 2021). "In addition, only one patient whose tumor was originally classified as BRAF wild-type, and subsequently flagged as BRAF mutation-positive by the cell-free assay, went on to receive and benefit from targeted therapy with cobimetinib plus vemurafenib." (PMID 34298804, 2021). "In tumor case 39, BRAF p.V600E mutation was present at a clonal allele frequency of 35%, indicating that it was likely to have been acquired as an early event during tumorigenesis and to be present in the majority of tumor cells in the heterozygous state." (PMID 34661724, 2021). "Hence, molecular features such as MSI and KRAS and BRAF mutations have clear clinical implications and have become essential predictors beyond regular image-based tumour staging." (PMID 34694371, 2021). "Additionally, resistance to BRAF inhibitors is associated with increased expression of PD-L1 by tumor cells, further suggesting PD-1 blockade would synergize with BRAF inhibition." (PMID 34025662, 2021). "The remarkably therapeutic efficacy may be induced by increased virus replication as we have determined that MEKi treatment enhanced oHSV replication in BRAF wt/KRAS mutated tumor cells in vitro." (PMID 34578339, 2021). "Similarly, the loss of neurofibromin 1 (NF1) observed in BRAF mutant tumour cells leads to intrinsic resistance through the loss of NF1 inhibition of RAS and MAPK signalling." (PMID 34066022, 2021).
tumor (continued). "Another compelling question is whether primary tumor location affects the outcome in BRAF-mutated mCRC treated with triplet therapy." (PMID 34946284, 2021). "In 2017, based on the demonstration that each of the tumor’s components harbors a distinct somatic mutation (i.e., BRAF mutation in the epithelial component and CTNNB1 mutation in the mesenchymal component), we proposed the term “papillary thyroid carcinoma with desmoid-type fibromatosis” (PTC-DTF)." (PMID 34503292, 2021). "Alternatively, in order for BRAF p.V600E to lead to tumour formation, the mutation may need to occur in a differentiated pituitary cell or adult pituitary stem cell rather than in an embryonic pituitary progenitor." (PMID 33795686, 2021). "In that study tumor thickness was significantly associated with BRAF positivity." (PMID 34567185, 2021). "Interestingly, both types of BRAF alterations were responsive to selumetinib, though the response rate was higher in tumours with BRAF fusions than in those with BRAF V600E mutation." (PMID 34360713, 2021). "The tumor tested positive for BRAF V600E mutation by immunohistochemistry." (PMID 34301805, 2021). "Another and more likely explanation of this discordance is that detection of RAS/BRAF mutation in ctDNA could be negatively affected by the low tumor load." (PMID 34680277, 2021). "BRAF mutant tumours are associated with poorer prognosis; in particular, the BRAFV600E mutation is associated with a lack of response to anti-EGFR therapies (such as cetuximab) if not treated simultaneously with an anti-BRAFV600E treatment (such as encorafenib)." (PMID 34945008, 2021). "Besides, the predictive value of radiomics was also applied in other aspects, such as the prediction of distant metastasis, tumor extrathyroidal extension, disease-free survival, and BRAF mutation." (PMID 34069887, 2021). "Among preBRAF- patients, BRAF mutation continued undetectable during tumor response." (PMID 34853302, 2021). "BRAF mutations could regulate the tumour immune microenvironment by regulating the pyroptosis-related signalling pathway." (PMID 34226539, 2021). "Of 100 patients with isolated CRC‐LM, 57 (57%) had a KRAS or BRAF tumor tissue mutation." (PMID 33635598, 2021). "Therefore, CT-based parameters cannot replace determination of BRAF mutation status on tumor tissue." (PMID 33915880, 2021). "The BRAF V600E mutation may have a role in the initiation and promotion of colorectal tumorigenesis through the serrated neoplasia pathway." (PMID 33530449, 2021). "Moreover, some in vitro studies demonstrated that MYC is a key element in tumor progression and treatment resistance of BRAF-mutated CRC." (PMID 34943546, 2021). "Thus, there was 100% concordance between the ddPCR tumor assay and mutational status as determined by SNapShot or IHC and 100% sensitivity and specificity for the diagnosis of BRAF V600E mutation in tumor tissue." (PMID 33799709, 2021). "In all preBRAF+ cases, BRAF mutation became undetectable at tumor response." (PMID 34853302, 2021). "In addition, TMS1 contains significantly more tumours with MSI-H (34.8%) and BRAF mutation (15.2%) compared to other tumour microbial subtypes." (PMID 34638284, 2021). "For example, we estimated the MSCs of BRAF mutations among various tumor types." (PMID 34424899, 2021). "Mutations in BRAF were detected in 21 (42%) tumours, of which 15/21 (71%) were in the V600 hotspot." (PMID 33024263, 2021). "Similarly, somatic mutation of BRAF is common in sporadic tumours with MSI but very rarely occurs in tumours arising in LS." (PMID 34944866, 2021). "It is well established that PTC is MAPK-driven with distinct consequences depending whether the tumor harbors BRAF V600E or RAS mutations." (PMID 34680332, 2021). "Two (29%) tumours harboured BRAF mutations p.D594G and p.K601E." (PMID 33737597, 2021).